CTSB (cathepsin B)
Diseases named in the same sentence as CTSB in open-access papers (continued):
Sharing a sentence is not in itself a finding about the gene and the disease.
breast carcinoma (continued). "We have recently demonstrated a critical role for tumor-derived cathepsin B using the syngeneic 4T1.2 model of murine breast cancer metastasis." (PMID 26308073, 2015). "A proteomic study recently demonstrated that cathepsin B expression in MDSCs isolated from mice bearing 4T1 tumors was three-fold increased compared to cells isolated from mice bearing 67NR mammary tumors." (PMID 26308073, 2015). "Elevated levels of CTSB expression have been reported in prostate cancer, colorectal cancer, gliomas, melanomas, breast cancer." (PMID 24139065, 2013). "Overexpression of human cathepsin B in MMTV-PyMT mice resulted in increased vascular density within the breast cancers and anti-angiogenic efficacy of an antibody targeting cathepsin S was shown in xenograft models." (PMID 22798952, 2012). "Compelling evidence for a major role of cathepsin B and related proteinases in tumor invasion and metastasis has been derived from pancreatic and breast cancer models in cathepsin knock-out mice." (PMID 22521359, 2012). "Sevennich and colleagues proved that combined inhibition of Cathepsin B and Cathepsin Z inhibited breast cancer metastasis in mice." (PMID 21966391, 2011). "As a result, in breast cancer, the cathepsin B and L activities were found to be much more increased than the respective protein levels, suggesting that the increase in activity was not entirely due to the induction of the respective proteins." (PMID 15138478, 2004). "Cathepsin B and L mainly showed expression by breast cancer cells." (PMID 39331316, 2024). "The researchers suggest that the interaction between fibroblasts and type I collagen in breast cancer may enhance the translation or stability of CTSB." (PMID 39264885, 2024). "Elevated levels of cathepsin B expression have been documented across diverse cancer types, including lung squamous cell carcinoma, prostate cancer, colorectal cancer, gliomas, melanomas, and breast cancer." (PMID 38500921, 2024). "Mainly cathepsin B and L showed expression by breast cancer cells." (PMID 39331316, 2024). "Interestingly, inflammatory breast cancer cells have been identified as particularly benefitting from cathepsin B abundance." (PMID 36002710, 2023). "Cystatin C significantly inhibited SAHA-induced CTSB expression in breast cancer cells." (PMID 37576397, 2023). "The malignant progression of the cancerous cells and tumour formation is exacerbated by reduced levels of the endogenous inhibitors used to regulate the cathepsin peptidases, such as cystatin C that regulates cathepsin B in cases of tongue cancer and breast cancer." (PMID 35214614, 2022). "Interestingly, emerging lines of evidence are also pointing to the pro-metastatic role of cathepsin B in bone metastasis of breast cancer." (PMID 35488278, 2022). "Hence, CREG1 was a strong candidate to explain the ameliorated phenotype of CTSB knock-out in the MMTV-PyMT breast cancer model." (PMID 32385587, 2021). "Specifically, S100A10 in a heterotetramer with Annexin II can act as co-receptor for tPA, plasminogen and pro-cathepsin B to promote invasion and metastasis in breast carcinoma and glioma cells, but it can also affect macrophage invasion and breast cancer cell proliferation." (PMID 33809973, 2021). "Besides that, a high abundance of BAG2 regulates the pro-cathepsin B/annexin II complex formation and facilitates the secretion of pro-cathepsin B, which induce metastasis in breast cancer." (PMID 34571787, 2021). "Additionally, our previous study revealed that BAG2 stimulates distant metastasis by promoting the secretion of pro-cathepsin B in breast cancer." (PMID 34572878, 2021). "Positive controls for cathepsin B (brown), cathepsin D (brown) and cathepsin G (brown) demonstrated the expected staining patterns in human placenta, breast carcinoma and mouse bone marrow, respectively." (PMID 30177970, 2018).
breast carcinoma (continued). "Interestingly, overexpression of cathepsin B attenuated the archazolid-induced adhesion of breast cancer cells onto endothelial cells, indicating that the adhesion negatively correlates with the expression of cathepsin B." (PMID 30204757, 2018). "In light of the inferred associations between SAHA-induced autophagy and CTSB activity, we hypothesized that SAHA-CTSB may activate molecular mechanisms conducive to the autophagy in breast cancer cells." (PMID 28881816, 2017). "Next, we determined whether TRAIL DR5 regulates SAHA-induced CTSB expression in breast cancer cells." (PMID 29018571, 2017). "Additionally, we identified a number of genes, as well as MAPK signaling that is potentially involved in the action of SAHA and CTSB in the breast cancer cells." (PMID 28881816, 2017). "In addition, we identified a number of genes, as well as the mitogen-activated protein kinase (MAPK) signaling that is potentially involved in the action of SAHA and CTSB in the breast cancer cells." (PMID 28881816, 2017). "Next, the changes in the levels of CTSB protein in breast cancer cells were assessed." (PMID 29018571, 2017). "Cystatin C, a CTSB inhibitor (CBi), was also detected in breast cancer cells and its interaction with CTSB may play an important role in breast cancer invasion and metastasis." (PMID 28881816, 2017). "The aim of the present study is to investigate whether or not the autophagy-related genes are induced by SAHA via the activation of CTSB in breast cancer cells." (PMID 28881816, 2017). "Lastly, we clarified that the mitogen-activated protein kinase (MAPK) signaling may involve in the action of SAHA and CTSB in the breast cancer cells." (PMID 28881816, 2017). "CTSB knockdown in breast cancer cells may inhibit CTSB activity and attenuate ECM degradation through reduced type I collagen activity and bone metastasis in vivo." (PMID 27031837, 2016). "Others have shown that PI3K mediates cathepsin B secretion by lysosomal exocytosis, and therefore increased secretion of cathepsin B may be one mechanism by which HRG increases its extracellular activity in breast cancer cell lines." (PMID 25668816, 2015). "Finally, we investigated the expression and activity of extracellular cathepsin B, as this has been implicated in mediating invasive behavior of HER2-positive breast cancer cells, and activation of MMP-9 and infiltrative tumor cell growth in glioma." (PMID 25668816, 2015). "Upon light activation, compound 2, like compound 1, inhibited cathepsin B activity and pericellular collagen IV degradation by the 3D pathomimetic models of living breast cancer cells, without causing toxicity." (PMID 26562785, 2015). "The proteomic comparisons notably led to the identification of five proteins that are used as breast cancer diagnostic and prognostic biomarkers: proliferating cell nuclear antigen (PCNA), cathepsin D, cathepsin B, protein S100-A14, and heat shock protein beta-1 (HSP27)." (PMID 22384035, 2012). "Furthermore, transgenic mice overexpressing human cathepsin B have been found to develop breast cancer metastasis at a much higher rate than their control littermates." (PMID 22521359, 2012). "Notably, orthotropic injection of murine 4T1.2 mammary cancer cells into the mammary gland fat pad and subsequent systemic administration of the highly selective cathepsin B inhibitor CA-074 reduced bone metastasis, while JPM-OET did not." (PMID 22798952, 2012). "Cathepsin B promotes progression and metastasis in mammary cancer, and the enhanced expression of cathepsin inhibitor Stefin A inhibits distant metastasis in primary breast cancer." (PMID 21966391, 2011). "Overexpression of CTSB in breast cancer has been shown to enhance tumor growth and invasion." (PMID 21199580, 2011).
breast carcinoma (continued). "Studies using animal models have demonstrated that TAMs are the primary source of high levels of cathepsin B or cathepsin S in prostate, pancreatic islet cancers, and mammary tumors, and its expression by TAMs plays critical roles in multiple stages of tumor growth and metastasis." (PMID 21595995, 2011). "The current study investigated the expression of cathepsin B, L, and S in breast cancer TMAs to determine which patient and tumor characteristics are associated with expression of these proteases and which patients might therefore benefit from intraoperative, cathepsin-targeted NIR FI." (PMID 39331316, 2024). "Therefore, this immunohistochemical study explores cathepsin B, L, and S expression levels in a large breast cancer patient cohort, to investigate in which breast cancer patients the use of cathepsin-targeted NIR FI may have added value." (PMID 39331316, 2024). "Therefore, we suspect CTSB may dictate Dox-induced autophagy- and apoptosis-mediated cell death in breast cancer cells." (PMID 35625886, 2022). "In addition, in MCF-7 breast cancer cells CTSB is upregulated while it suppresses E-cadherin." (PMID 33809973, 2021). "Therefore, we performed a quantitative secretome comparison using differential isotope labeling of the cell-conditioned medium (CCM) of co-cultures comprising PyMT breast cancer cells and Mɸ either wild type or double knock-out for CTSB and CTSZ (Mɸ Ctsb−/−; Ctsz−/−)." (PMID 32385587, 2021). "To evaluate the efficacy of the CtsB-targeting liposome delivery system, we first verified that CtsB is expressed and secreted by the primary tumor cells derived from a genetically engineered mouse model of breast cancer (MMTV-PyMT)[6d and by the primary mouse macrophages." (PMID 24975267, 2014). "Supporting this hypothesis, breast cancer cells co-expressing Cav-1 and cathepsin B exhibit higher malignancy than other cells owing to their increased invasion and metastasis, which is likely attributed to increased secretion of cathepsin B and subsequent extracellular matrix degradation." (PMID 40135201, 2025). "Cathepsin B is crucial in promoting tumour invasion and metastasis across a spectrum of cancers, including hepatocellular carcinoma (HCC), breast cancer, melanoma, lung cancer, and head and neck cutaneous squamous cell carcinoma (SCC)." (PMID 38500921, 2024). "Cathepsin B (CATB), a lysosomal protease, is overexpressed in human breast cancers with high metabolic activity and is correlated with poor prognosis." (PMID 34681079, 2021). "In breast cancer, MZF1 activates the expression of cathepsin B to increase the invasion of cancer cells." (PMID 32042322, 2020). "In a biochemical assay that checks the leakage of lysosomal enzymes into the cytosol, we observed a pronounced leakage of both cathepsin D and cathepsin B to the cytosol in PC3 prostate and MDA-MB-231 breast cancer cells." (PMID 31412041, 2019). "In the case of cathepsins, CTSB, CTSD, CTSK, CTSL, and CTSS were expressed in all breast cancer cells; however, the mRNA and protein expression of CTSS was much higher in the TNBC cell lines compared to the hormone-responsive cell lines." (PMID 30185799, 2018). "The role of CTSB and CTSS in breast cancer cell survival and invasion was also confirmed with the use of pharmacological inhibitors that were specific for each cathepsin." (PMID 30185799, 2018). "ELISA was performed to confirm the altered expression levels of PRDX2, PRDX6, CTSB and CTSD in the serum among the breast cancer patients and healthy volunteers as a representative sample in order to validate the serum levels." (PMID 24932247, 2014). "An additional protein family of interest is the CTS proteins; in the present study, five CTS proteins (CTSB, CTSC, CTSD, CTSH and CTSZ) were identified to be upregulated in breast cancer." (PMID 24932247, 2014).
breast carcinoma (continued). "CTSB along with CTSL was found to be overexpressed in HER2 positive cancers and is an important mediator of tumor invasion in this subtype of breast cancer." (PMID 24086418, 2013). "MZF1 is a transcription factor that regulates ErbB2-induced invasion of breast cancer cells by inducing expression of cathepsin B (CTSB) and the outward transport of lysosomes to the plasma membrane, where the exocytosis of cathepsin B and other lysosomal hydrolases contribute to cancer invasion." (PMID 37420029, 2023). "Furthermore, breast cancer cell-derived CST6 enters osteoclasts through endocytosis and upregulates the hydrolysis substrate of CTSB, SPHK1, by inhibiting CTSB." (PMID 37860014, 2023). "There is an important correlation between CTSB and SAHA-induced breast cancer cell autophagy." (PMID 28881816, 2017). "IC50 valuesa (μM) for compounds 1 and 2 and dark/light ratio (with and without irradiation) against human CTSB and human breast cancer cell lysates." (PMID 26562785, 2015). "Here, our studies indicate that the IL-8 level is significantly elevated in melanoma but not in breast cancer patients, while the Cathepsin B level is higher in both melanoma and breast cancer as compared with healthy subjects." (PMID 21673904, 2011). "Therefore, this immunohistochemical study explores CTSB, CTSL, and CTSS expression levels in a large breast cancer patient cohort, to investigate in which BCa patients the use of cathepsin-targeted NIR FI may have added value." (PMID 39331316, 2024). "Moreover, a regulatory loop has been proposed in breast cancer, in which an increased expression of CXCL9 and/or CXCL10 leads to induction of cathepsin B gene expression and, in consequence cathepsin B protein levels, which then may reduce chemokine activity." (PMID 31482487, 2019). "In order to explore whether or not CTSB is also involved in the action of SAHA on breast cancer cells, we used western blot and ELISA assay to determine CTSB protein levels in breast cancer cells upon SAHA treatment." (PMID 28881816, 2017). "Similarly, high expression of the cathepsin family of proteases (CTSC, CTSZ, CTSB) was found to be indicative of poor prognosis in breast cancer patients but appeared to have no significant predictive value in prostate cancer patients." (PMID 17183660, 2006). "Moreover, TAM-derived cathepsins especially cathepsin S and cathepsin B might be one of the mechanisms contributing to TAM-mediated tumor chemoresistance in breast cancer, protecting murine mammary tumor cells from paclitaxel-, doxorubicin-, etoposide-induced cell death." (PMID 39003350, 2024). "There was no substantial change in cathepsin B expression following treatment with exogenous HRG, but there was a significant increase in extracellular cathepsin B activity in all three breast cancer cell lines." (PMID 25668816, 2015).
glioma (72 papers, 2007 to 2026). A benign or malignant brain and spinal cord tumor that arises from glial cells (astrocytes, oligodendrocytes, ependymal cells). "In conclusion, caffeine impairs the invasion ability of glioma cells through the Rho-associated protein kinase–cathepsin B/FAK/ERK pathway." (PMID 37398678, 2023). "In glioma-initiating cells (GICs), downregulation of uPAR and CTSB caused a transcriptional arrest and sensitized glioma cells to apoptosis by inhibiting c-Met signaling." (PMID 37576397, 2023). "The survival analysis showed that the highly-expressed CTSB means shorter OS time of glioma patients, which is also an independent risk factor for the prognosis, and the similar result was reported before in GBM38." (PMID 35277559, 2022). "More importantly, the levels of glioma-infiltrating immune cells were positively associated with the expression of CTSB, especially for TAMs, MDSCs and Tregs." (PMID 35277559, 2022). "Correlation analysis confirmed that glioma-associated immune response and inflammatory activity are significantly correlated with CTSB." (PMID 35277559, 2022). "CTSB has more recently been implicated in stem cell maintenance, as demonstrated in glioma-initiating cells." (PMID 30796200, 2019). "Because of the known involvement of PI3K/Akt and MAPK/ERK signaling pathways in the activation of cathepsin B, a similar cysteine protease, in glioma, Cat X activity is likely associated with these same pathways." (PMID 29423430, 2017). "According to the clinical meaning of these molecular phenotypes in gliomas, patients with highly-expressed CTSB may have a greater risk of tumor recurrence, progression, epithelial mesenchymal transformation (EMT) and therapeutic resistance." (PMID 35277559, 2022). "In addition, our analysis of the REMBRANDT database shows that upregulated cathepsin B gene expression is associated with a shorter overall survival for the group of all glioma." (PMID 24743710, 2014). "The acidic extracellular environment induced glioma cells to produce cathepsin B, which boosted glioma cell invasion." (PMID 38336645, 2024). "In vitro glioma experiments showed that the inhibition of cathepsin B resulted in the downregulation of MMP-9 and VEGF expression." (PMID 37398678, 2023). "CCK-8 and colony formation assays showed that CTSB overexpression prevented ar-turmerone treatment from inhibiting glioma cell proliferation and colony formation, respectively." (PMID 37768200, 2023). "In this study, we observed that CTSB mRNA levels in glioma cells decreased following ar-turmerone treatment in vitro." (PMID 37768200, 2023). "Additional qRT-PCR analyses revealed that CTSB levels were higher in glioma cell lines (U87, U251 and LN229) than in normal human astrocytes (NHA cells)." (PMID 37768200, 2023). "In our own research cohort, we also found that the CTSB mRNA expression was higher in glioma tissues than in adjacent tissues." (PMID 37768200, 2023). "CTSB has been shown to cleave P27 and promote cell cycle arrest; thus, we assessed the expression of proteins downstream of CTSB in glioma cells after ar-turmerone treatment." (PMID 37768200, 2023). "In conclusion, ar-turmerone suppressed cathepsin B expression and P27 cleavage, thereby inhibiting the proliferation and mobility of glioma cells." (PMID 37768200, 2023). "We found that CTSB expression was higher in glioma tissues than in adjacent tissues, and that CTSB overexpression significantly disinhibited the proliferation and migration of ar-turmerone-treated glioma cells." (PMID 37768200, 2023). "We then conducted a flow cytometry analysis, which demonstrated that CTSB overexpression significantly reversed the inhibitory effects of ar-turmerone on G1/S phase in glioma cells." (PMID 37768200, 2023). "Ar-turmerone treatment reduced cathepsin B expression and inhibited the cleavage of its target protein P27 in glioma cells." (PMID 37768200, 2023).